DIO2 (iodothyronine deiodinase 2)
Description:
Plays a crucial role in the metabolism of thyroid hormones (TH) and has specific roles in TH activation and inactivation by deiodination. Catalyzes the deiodination of L-thyroxine (T4) to 3,5,3'-triiodothyronine (T3), 3,3',5'-triiodothyronine (rT3) to 3,3'-diiodothyronine (3,3'-T2) and 3',5'-diiodothyronine (3',5'-T2) to 3'-monoiodothyronine (3'-T1) via outer-ring deiodination (ORD). Catalyzes the phenolic ring deiodinations of 3,3',5'-triiodothyronamine and 3',5'-diiodothyronamine.
Synonyms: TXDI2; SelY; SELENOY; 5DII; D2; DIOII
Tractability: Antibody: its Gene Ontology location is reachable by antibodies, with high confidence; UniProt predicts a signal peptide or a membrane-spanning region; the Human Protein Atlas places it where antibodies can reach. PROTAC: UniProt records ubiquitination sites on it.
Safety:
Unwanted effects reported when the protein is acted on. In parentheses: how it was acted on, where the effect was seen, and who reports it.
Decrease, Population growth rate (inhibition; source: AOP-Wiki)
Increased Mortality (inhibition; source: AOP-Wiki)
Altered, Amphibian metamorphosis (inhibition; source: AOP-Wiki)
Gene: Protein-coding gene on chromosome 14 (80,197,526 to 80,387,757, reverse strand). Ensembl gene ENSG00000211448.
Subcellular location: Endoplasmic reticulum membrane
Subcellular location (Human Protein Atlas): Nucleoplasm; Vesicles; Plasma membrane
Pathways (Reactome):
Developmental Biology: Transcriptional regulation of brown and beige adipocyte differentiation by EBF2
Metabolism: Regulation of thyroid hormone activity
Gene Ontology:
Molecular function: thyroxine 5'-deiodinase activity; thyroxine 5-deiodinase activity; ubiquitin protein ligase binding; selenium binding
Biological process: thyroid hormone catabolic process; thyroid hormone metabolic process; positive regulation of cold-induced thermogenesis; selenocysteine incorporation; thyroid hormone generation; response to lipopolysaccharide
Cellular component: endoplasmic reticulum membrane; membrane
Genetic constraint (gnomAD): Loss-of-function variants: 19 observed, 21.67 expected, observed/expected ratio (o/e) 0.88, 90% interval 0.61 to 1.29. The upper end of that interval is the gene's LOEUF score, 1.29, which puts it in group 5 of 6, group 1 being the genes least tolerant of losing a copy. Missense variants: 302 observed, 349.09 expected, observed/expected ratio (o/e) 0.87, 90% interval 0.79 to 0.95. Synonymous variants: 122 observed, 138.22 expected, observed/expected ratio (o/e) 0.88, 90% interval 0.76 to 1.03.
Homologues: Orthologues: pig DIO2 (91% identical), rat Dio2 (88% identical), mouse Dio2 (88% identical), guinea pig DIO2 (85% identical), zebrafish dio2 (66% identical), macaque DIO2 (47% identical), dog DIO2 (45% identical), chimpanzee DIO2 (31% identical). Paralogues in human: DIO3 (34% identical), DIO1 (33% identical).
Diseases named in the same sentence as DIO2 in open-access papers:
DIO2 is named in the same sentence as 73 diseases in open-access papers, as found by Europe PMC text mining. Sharing a sentence is not in itself a finding about the gene and the disease. The quoted sentences say what the papers report.
Obesity (27 papers, 2015 to 2025). Accumulation of substantial excess body fat. "Specifically, Dio2-KO was shown to increase susceptibility to HFD-induced obesity with both adipose tissue and ectopic fat accumulation, as well as insulin resistance." (PMID 32344656, 2020). "The disruption of TH activation in Dio2 knockout mice caused obesity, glucose intolerance, and liver steatosis under conditions of thermoneutrality but not at ambient temperature." (PMID 33374300, 2020). "Studies in animals have demonstrated that knockout of dio2 increased the susceptibility to diet-induced obesity while animals with thra knockout were highly vulnerable to low temperatures due to the complete lack of BAT reactivity to noradrenergic stimulation." (PMID 25622596, 2015). "Mice with obesity were treated with oral avocado seed extract, observing reduced BW and enhanced expression of deiodinase 2 (Dio2) in the ARC." (PMID 41550864, 2025). "Rutin has been shown to protect mice from HFD-induced obesity and adipocyte hypertrophy, and to up-regulate the transcription of genes (deiodinase 2 (Dio2), Elovl3, PGC-1α, UCPs) involved in energy expenditure in BAT and to maintain glucose sensitivity." (PMID 31346342, 2019). "Using this model of Dio2 knockdown, we sought to determine the contribution of elevated Dio2 in the development of GC-induced hyperphagia and obesity." (PMID 31176677, 2019). "Dio2 regulation by a classic lipogenic transcription factor was observed in LXRα and LXRβ double KO mice, which ectopically express Dio2 in the liver, suggesting a role for Dio2 inhibition in hepatic lipid deposition and obesity." (PMID 26861388, 2016). "Diet-induced obesity in male mice has also been demonstrated to depend on Dio2 activity in the anterior pituitary activated by the c-Jun N-terminal kinase (JNK) pathway, controlling TSH levels and consequent thyroid hormone-dependent energy expenditure." (PMID 26861388, 2016). "Mice with targeted disruption of Dio2 (Dio2 KO) lack proper adaptive thermoregulation and are more prone to high fat diet-induced obesity." (PMID 26861388, 2016). "Future studies are warranted to directly test whether BAT TGR5 or Dio2 is required for L1-KO mice to resist HFD-induced obesity." (PMID 34943976, 2021). "However, as a gene that regulates fat synthesis, researchers usually achieve anti-obesity effects by inhibiting Dio2 and PPARγ." (PMID 31817377, 2019). "However, the obesity phenotype is only observed at thermoneutrality (30°C) but not at 22°C in the Dio2 deficient mice, whereas it occurs at lower temperatures (~25°C) in the OT, OTR and Bmp8b deficient mice." (PMID 39345420, 2024). "These processes were correlated with the increased gene expression of Dio2 and Ucp-1, which represents brown adipose tissue (BAT) activation, in both WD-induced atherosclerosis and high-fat-induced obesity models." (PMID 31570705, 2019). "The 7CafD females developed a less favourable obesity phenotype than 7CafD males: they accumulated more WAT, and exerted a reduced expression of FAO genes (Cpt1β and Ucp3) in muscle and of the thermogenic gene (Dio2) in WAT." (PMID 39596499, 2024). "However, neonatal hepatocyte-specific Dio2-KO impaired response to HFD, resulting in alteration of lipid metabolism and PPARy expression, as well as lower rate of obesity and hepatic steatosis." (PMID 32344656, 2020). "Alpha-KG not only increases the expression of thermogenic genes (i.e., Ucp1, Dio2, and Cidea) in the BAT, but also enhances lipolysis in the WATs through OXGR1-dependent adrenal activation, and as a result, administration of exogenous α-KG prevents HFD-induced obesity in mice." (PMID 40959283, 2025). "The mRNA levels for Dio2 were not affected by obesity when compared to controls." (PMID 34714995, 2021).
Obesity (continued). "However, knockdown of Dio2 using AAV-mediated CRISPR-Cas9 vectors targeted to the MBH conferred no protection from GC-induced hyperphagia or obesity in this setting, providing evidence that other mechanisms mediate the metabolic sequelae resulting from chronic GC treatment." (PMID 31176677, 2019).
hypothyroidism (18 papers, 2014 to 2025). Abnormally low levels of thyroid hormone. "Accordingly, a mouse with glial-cell selective inactivation of the gene encoding D2 (Dio2) exhibits a mood and cognitive phenotype typical of hypothyroidism." (PMID 37204837, 2023). "In line with low bone turnover activity, cortical bone strength at the femur and thus likely bone quality were impaired with hypothyroidism compliant with increased bone fragility seen in Dio2-deficient mice with a local hypothyroid state in bone." (PMID 36143246, 2022). "Transcriptional levels of deiodinases were more elevated in exposed zebrafish, in accordance with a study reporting that hypothyroidism caused by EDCs is associated with higher activity and expression of Dio2." (PMID 32294918, 2020). "Differently from mice, the detected hypothyroidism has been suggested by the inhibition of Dio3 transcripts beyond the increment of Dio1 and Dio2 mRNAs." (PMID 36769379, 2023). "Within eWAT, low expression of Klf9 while high expression of deiodinase 2 (Dio2), an enzyme that can convert T4 to T3, indicated local hypothyroidism in treated mice." (PMID 36143246, 2022). "Previously, reproductive dysfunction with relatively normal gamete development was observed in two hypothyroidism models: duox and dio2 zebrafish mutants." (PMID 34440752, 2021). "Previous findings show that enhanced dio2 activity increases the proportion of T3 formed locally in dio2-expressing tissues (such as the brain) under hypothyroidism conditions to mitigate the decrease of tissue T3 content." (PMID 34545202, 2021). "It was demonstrated that hypothyroidism was related to the increase of dio2 and/or dio1 mRNA expression, when zebrafish larvae were exposed to other environmental pollutants." (PMID 28467477, 2017). "The model also explains why the double inactivation of Mct8 and Oatp1c1 transporters leads to a situation in the brain similar to hypothyroidism, as in the double Mct8 and Dio2 KO." (PMID 24910631, 2014). "In this study, both Dio1 and Dio2 were significantly induced after MEHP exposure, consistent with previous study demonstrating that hypothyroidism increases Dio1 and Dio2 activities and mRNA expression." (PMID 24658602, 2014). "Single inactivation of the Dio2 gene in mice leads to brain T3 concentrations similar to hypothyroidism, but relatively minor effects on gene expression." (PMID 24618783, 2014). "For example, in profound hypothyroidism in the rat, Dio2 expression was also observed in a fraction of cerebral cortex interneurons." (PMID 24910631, 2014). "Daily treatment with Kp-10 did not alter the higher protein expression levels of VEGF, HIF1α, IL10, GRP78, and CHOP caused by hypothyroidism in the junctional zone compared to control, nor the lower expression of Dio2 caused by hypothyroidism." (PMID 35966095, 2022). "The authors suggested that this could be due to upregulation of Dio2 and local increase of T3 as the double knockout of Dio2 showed similar effects as hypothyroidism." (PMID 33685490, 2021). "Hypothyroidism has been recently demonstrated to increase dio2 mRNA expression." (PMID 26501309, 2015). "Although Dio2-KO mice display elevated brain T4 levels and reduced T3 content, surprisingly, the observed neurological impairments, which included changes in the cerebellar expression of TH-dependent genes and behavioral defects, were found to be mild compared with those observed in hypothyroidism." (PMID 24904526, 2014). "Thus, our results suggest a decrease in T3 local availability in the hippocampus, as Dio2 expression, as not increased, would not allow the compensation of the lower T4 levels entering the cells, due to the circulating hypothyroidism." (PMID 36233235, 2022). "Consequently, compound inactivation of Mct8 and Dio2 leads to a situation more similar to hypothyroidism, but surprisingly some genes profoundly affected in the hypothyroid brain such as Aldh1a1 are not affected by concomitant Mct8 and Dio2 inactivation." (PMID 24618783, 2014).
Insulin resistance (15 papers, 2008 to 2025). Increased resistance towards insulin, that is, diminished effectiveness of insulin in reducing blood glucose levels. "During prediabetes, the conversion of FT4 to FT3 is impaired due to decreased activity of type 1 deiodinase (DIO1) and type 2 deiodinase (DIO2), and this can be attributed to the oxidative stress associated with insulin resistance." (PMID 40076791, 2025). "Another study also showed that the rs225017 polymorphism in the 3′UTR of the human DIO2 gene was associated with greater insulin resistance (IR) and interacted with the Thr92Ala polymorphism in the modulation of IR." (PMID 34727635, 2022). "In humans, a common polymorphism of the Dio2 gene, the Thr92Ala substitution in protein D2, which partially impairs enzymatic activity, has been correlated with insulin resistance and diabetes." (PMID 30254607, 2018). "In humans, D2 has been linked to insulin resistance, with a polymorphism in the human Dio2 coding region (Thr92Ala) found at a frequency of 0.32 in the general population, and 0.75 in Pima Indians, being associated with insulin resistance in some studies." (PMID 21698184, 2011). "A single nucleotide polymorphism in the Type 2 deiodinase (DIO2) gene (p.Thr92Ala) was found to be associated with hypertension, type 2 diabetes mellitus (T2DM), insulin resistance, and body mass index (BMI)." (PMID 35739305, 2022). "It was shown that single-nucleotide polymorphism Thr92Ala in the coding region type 2 iodothyronine deiodinase, encoded by DIO2, is associated with insulin resistance." (PMID 35456211, 2022). "In summary, our results indicate that a loss of the Dio2 gene in mice results in greater weight gain, hepatic steatosis on a HFD, and insulin resistance even before D2KO mice have increased adipose tissue." (PMID 21698184, 2011). "Inactivation of deiodinase II (DIO2) enzyme by a Vitamin D deficient environment in patients with DM leads to decreased glucose transporter 4 (GLUT4) transcription by skeletal muscle and adipose tissue, thus resulting in insulin resistance and thyroid carcinogenesis." (PMID 36213272, 2022). "An experimental study observed that mice with a disrupted Dio2 gene (D2KO) were susceptible to diet-induced obesity and insulin-resistance independent of obesity and suggested involvement of D2 activity in the development of metabolic abnormalities." (PMID 24872812, 2014). "In addition, the decreased level of Dio2-generated T3 might also inhibit the transcription of GLUT4 in insulin-sensitive tissues, such as adipose tissue or skeletal muscle, which could lead to insulin resistance." (PMID 34660805, 2021).
depression (8 papers, 2020 to 2025). "Genetic studies have shown that polymorphism of the DiO2 gene (rs225014; Thr92Ala) is associated with depression, and heterozygote polymorphism has been associated with an increased risk of BD." (PMID 37511721, 2023). "Genetic studies have shown that polymorphism of the DiO2 gene (rs225014; T92A) is associated with depression, and heterozygote polymorphism has been associated with an increased risk of bipolar disorder." (PMID 36233698, 2022). "This was consistent with results from mice models with cerebral astrocyte-specific Dio2 inactivation and reduced T3 level, which exhibited anxiety-depression-like behavior in the OFT, FST and TST." (PMID 37259424, 2023). "In addition, the DiO1, DiO2 Thr92Ala, and SLCO1C1 mutation SNPs show a high sensitivity and specificity in differentiating depressive disorder from BSD." (PMID 37511721, 2023). "Interestingly, other authors demonstrated that mice with astrocyte-specific Dio2 inactivation exhibit anxiety-depression-like behaviour." (PMID 36233235, 2022). "Recent findings further highlight that SNPs in DIO1, DIO2 and SLCO1C1 showed high sensitivity and specificity in differentiating depressive disorder from BD, emphasising the role of genetic variations in TH pathways in delineating between different mood disorders." (PMID 40586856, 2025).
Anxiety (6 papers, 2020 to 2025). Intense feelings of nervousness, tension, or panic often arise in response to interpersonal stresses. "Interestingly, male mice with astrocyte-specific Dio2 inactivation have normal serum T3 but exhibit anxiety-depressive behavior linked to decreased hippocampal expression of classic TH-responsive genes." (PMID 41234240, 2025). "The diacylglycerol kinase gamma gene (DGKG) was reported to be negatively regulated by the triiodothyronine hormone in mice inactivated for astrocyte-specific Dio2, which resulted in mood and behavioral disorders, such as anxiety-depressive behavior." (PMID 36658485, 2023). "This is further demonstrated by the increase of hippocampal Dio2 expression and the decrease of the anxiety-like behaviour of the hypothyroid WSB/EIJ mice." (PMID 36233235, 2022).
Hypertension (6 papers, 2011 to 2022). The presence of chronic increased pressure in the systemic arterial system. "Currently, there are few studies on the issue regarding Dio2 polymorphism and hypertension risk; thus, our findings should be considered preliminary and require confirmation." (PMID 34660805, 2021). "A couple of type II iodothyronine deiodinase (DIO2) gene mutations were found to cause hypertension in middle-aged patients with euthyroidism." (PMID 31379748, 2019). "In humans, polymorphisms at the Dio2 locus determines susceptibility to hypertension and diabetes." (PMID 21291556, 2011).
diabetes (5 papers, 2011 to 2022). "The entire coding-region of DIO2 gene was sequenced in 12 patients with type 2 diabetes mellitus (T2DM)." (PMID 25105294, 2014).
type 2 diabetes mellitus (4 papers, 2014 to 2022). A type of diabetes mellitus that is characterized by insulin resistance or desensitization and increased blood glucose levels. "The rs225014 polymorphism of the DIO2 gene (iodothyronine 2 deiodinase) was associated with the occurrence of diseases such as: type 2 diabetes, osteoporosis, Hashimoto’s disease, Graves’ disease, Alzheimer’s disease and autism." (PMID 35205233, 2022).
hyperthyroidism (3 papers, 2021 to 2023). Overactivity of the thyroid gland resulting in overproduction of thyroid hormone and increased metabolic rate. "Whereas Dio2 activity is inversely related to fT4 concentration due to substrate-induced ubiquitination of the enzyme, Dio1 activity increased during hyperthyroidism." (PMID 36892852, 2023). "Intriguingly, on combining our observations on tshba, tg, and slc16a2 mutants and previous reports on two other hyperthyroidism zebrafish models, duox and dio2, the involvement of TH signaling in both LTJT, and SSC development can be found." (PMID 34440752, 2021).
liver disease (3 papers, 2011 to 2023). "It has been shown that Dio2 knockdown in fetal mice protects against liver disease later in life demonstrating that epigenetics can also play a major role in the effects of deiodinases." (PMID 36892852, 2023). "This study showed that rs225014 (DIO2), rs532446 (GADD45A), rs12031994 (AKT3), rs11119982 (ATF3), rs10865710 (PPARG) are associated with the increased risk of liver disease progression in chronic hepatitis b carriers." (PMID 37059745, 2023). "As a result, our study demonstrated that rs225014 (DIO2), rs532446 (GADD45A), rs12031994 (AKT3), rs11119982 (ATF3), rs10865710 (PPARG) might contribute to the increased risk of liver disease progression in chronic hepatitis b carriers." (PMID 37059745, 2023). "Furthermore, very intriguing results have been obtained for neonatal Dio2 affecting liver disease in adult life." (PMID 36892852, 2023).
liver steatosis (3 papers, 2011 to 2023). "Whereas Dio2 is not measured in adult liver, perinatal hepatic Dio2 expression influences susceptibility to liver steatosis." (PMID 36892852, 2023).
thyroid (3 papers, 2012 to 2021). "The change in activity of D2 is often greater than the change in Dio2 mRNA, for example in brown adipose tissue following cold exposure and the brain following experimentally induced hypo- and hyper-thyroidism." (PMID 23586759, 2013). "The 11 selected thyroid-specific RNA transcripts (TPO, TG, GFRA2, IYD, PDE8B, WDR86, C16orf89, DGKI, DIO2, TSHR, and PAX8) were amplified from healthy volunteers and thyroid patients." (PMID 34512731, 2021).
breast carcinoma (2 papers, 2020 to 2022). "Overall, considering both the CCLE and LINCS datasets, eight selenoproteins were overexpressed (DIO2, GPX1, GPX4, SELENOI, SELENON, SELENOS, TXNRD1 and TXNRD3) and five were down-expressed (DIO1, GPX2, GPX3, SELENOP and SELENOW) in TNBC compared to all other “non-TNBC” breast cancer subtypes." (PMID 35158912, 2022).